ABCB1 (ATP binding cassette subfamily B member 1)
Diseases named in the same sentence as ABCB1 in open-access papers (continued):
Sharing a sentence is not in itself a finding about the gene and the disease.
cancer (continued). "Recently, ABCB1 1236C/T and 2677G/T were found to be associated with the clearance of sunitinib in a study involving 114 cancer patients in the Netherlands." (PMID 26244574, 2015). "Overexpression of the ATP-binding cassette (ABC) transporter ABCB1/P-glycoprotein (P-gp) is one of the most common causes of MDR in cancer cells." (PMID 26006713, 2015). "The development of multidrug resistance (MDR) in cancers is also associated with the overexpression of ABCB1." (PMID 26327240, 2015). "Multidrug resistance in cancer is linked to expression of the P-glycoprotein multidrug transporter (Pgp, ABCB1), which exports many structurally diverse compounds from cells." (PMID 24624364, 2014). "The ABCB1 c.1236C>T, c.3435C>T and c.2677G>T/A polymorphisms have been associated with cancer risk, as well as the variability of response to chemotherapy treatments." (PMID 24660038, 2014). "Amplification, rearrangement and/or overexpression of ABCB1 have been associated with chemotherapy failure in many cancers." (PMID 25057852, 2014). "Overexpression of ABCB1 causes therapeutic drugs to be pumped out of the cancer cells thus preventing effective treatment." (PMID 25401518, 2014). "Overexpression of isoform I (ABCB1) in cancer cells was linked with resistance to multiple drugs, hence the name for this transporter multidrug resistance protein 1 (MDR1)." (PMID 23766564, 2013). "The major ABC-transporters involved in multidrug resistance in cancer cells are P-glycoprotein (MDR1, P-gp, ABCB1), multidrug resistance-associated proteins (MRPs, belonging to the ABCC sub-family), and the breast cancer resistance proteins (BRCP1, ABCG2)." (PMID 24135911, 2013). "Recently, Wnt signaling was linked to ABCB1 regulation through its canonical pathway, which is mediated by β-catenin, in other types of cancer." (PMID 22823957, 2012). "The overexpression of ABCB1 occurs in 40–50% of cancer patients, and is associated with a poor clinical outcome." (PMID 21552528, 2011). "One of the major causes of chemotherapy failure in cancer treatment is multidrug resistance (MDR) which is mediated by the ABCB1/P-glycoprotein." (PMID 21552528, 2011). "For instance, the promoter of the efflux transporter gene ABCB1, encoding P-glycoprotein, is hypomethylated in several cancer cell lines, thereby leading to a multidrug-resistance phenotype compared to drug-sensitive cell lines." (PMID 22196450, 2011). "By means of this model the data provide the proof-of-concept that tkRNAi is suitable for modulation of cancer-associated factors, e.g. ABCB1, in human cancer cells." (PMID 20811323, 2010). "A well-characterized cancer-associated target molecule for different RNAi strategies is ABCB1 (MDR1/P-glycoprotein, MDR1/P-gp)." (PMID 20811323, 2010). "This procedure resulted in activation of the RNAi pathways within the cancer cells and a considerable down regulation of the ABCB1 encoding mRNA as well as the corresponding drug extrusion pump." (PMID 20811323, 2010). "It has been recently shown, that synonymous SNPs in ABCB1 (P-glycoprotein), implicated both in determining drug pharmacokinetics and multidrug resistance in human cancer cells, can affect protein conformation and function." (PMID 20606865, 2010). "Similarly, the downregulation of ABCB1 expression in cancer cells is associated with a reduction in H3/H4ac, and changes in ABCB1 expression and/or activity can be observed with the use of HDAC inhibitors." (PMID 40265153, 2025). "Therefore, understanding the cancer specific upstream regulators of ABC transporters is necessary to circumvent the toxicity linked with direct inhibition of ABCB1." (PMID 40583060, 2025). "ABCB1 overexpression in cancers has often been associated with poor patient prognosis." (PMID 39003409, 2024). "However, we cannot exclude an effect on other cancer cell types, given that ABCB1 expression is also associated with the differentiated intestinal epithelial cells." (PMID 38693105, 2024).
cancer (continued). "Specifically, the ABCB1 rs1045642 and rs1128503 variants have been linked to alterations in transporter functionality or expression, as well as associated with the risk of certain cancers or drug-induced toxicity." (PMID 38675222, 2024). "A recent review reported that inhibiting ABCB1 could restore cancer cell susceptibility to chemotherapy drugs." (PMID 37601683, 2023). "The analysis performed with the U Mann–Whitney test showed that the average expression level of the ABCA2 (p = 0.01) and ABCB1 (p = 0.001) genes was statistically significantly higher in patients associated with the lymphatic vessel infiltration of cancer cells." (PMID 36674773, 2023). "ABCB1 gene polymorphisms may have a close relationship with the pain perception of cancer patients, thus affecting use of opioid drugs by patients." (PMID 37990344, 2023). "ABCB1—ABCB1 is a transporter gene that has been implicated in cancer drug resistance." (PMID 38304289, 2023). "To summarize, ABCB1 polymorphisms status may be one of the numerous factors that affect cancer development." (PMID 35627114, 2022). "For ABCB1, the picture is less clear, because several studies have identified variants linked to the prevalence of certain cancers and the outcome of treatments, and some of those variants could be under selection." (PMID 36445690, 2022). "Furthermore, low ABCB1 (P-glycoprotein) mRNA expression or truncation mutations are correlated with significantly longer survival in ovarian and other cancers." (PMID 35164068, 2022). "Multidrug resistance (MDR) mediated by ATP binding cassette subfamily B member 1 (ABCB1/P-gp) is a major cause of cancer chemotherapy failure, but the regulation mechanisms are largely unknown." (PMID 35459184, 2022). "It brings us to a well-known conclusion that ABCB1 polymorphism status may be one of the numerous factors contributing to the drugs’ metabolism in cancer cells." (PMID 35627114, 2022). "One of the essential ABC family proteins is ABCB1, which is responsible for drug pharmacodynamics, and according to literature data, it may contribute to increased cancer risk and/or resistance of cancer to drugs." (PMID 35627114, 2022). "Moreover, ABCB1 or ABCG2 overexpression in cancer cells is often associated with multidrug resistance (MDR) and poor prognosis in patients with solid tumors or hematologic cancers." (PMID 36361555, 2022). "Combining our findings that cdk6-deficient cancer cells lost ABCB1-mediated MDR via co-downregulating PI3K 110α/β, we deem that cdk6 could be a promising target for reversing ABCB1-mediated MDR and inhibiting cancer cell proliferation simultaneously." (PMID 35459184, 2022). "Thus cancer MDR is often associated with overexpression of ABC transporters such as ABCB1, ABCG2 and ABCC1, which have been proved to mediate the efflux of structurally distinct chemotherapeutic agents." (PMID 34631561, 2021). "Multidrug resistance (MDR) is a major cause of failure in cancer chemotherapy, as efflux of intracellular drugs by P-gp (the drug transporter MDR1 or ABCB1; overexpressed in multidrug resistant cancer cells) causes a decrease in the intracellular drug concentration." (PMID 34299488, 2021). "P-glycoprotein (P-gp or ABCB1) is the most well-characterized member of the human ATP-binding cassette (ABC) transporter family that has been linked to the development of multidrug resistance (MDR) in cancer." (PMID 34350184, 2021). "Noteworthy, the interpretation of ABCB1 mutations in cancer therapeutics could be influenced by cancer types, therapeutic regimens, and ABCB1 mutational classes." (PMID 34541464, 2020). "However, we did not confirm an observation noted by other authors that during cancer development the expression level is decreased which can be connected with the loss of physiological, protecting function of encoded by the ABCB1 gene protein." (PMID 32277145, 2020).
cancer (continued). "Moreover, the mutational spectrum of ABCB1 was further assessed in diverse types of cancer samples including AMLs in the Cancer Genome Atlas (TCGA) at the National Cancer Institute." (PMID 34541464, 2020). "As more ABCB1 sequencing data and detailed therapeutic information are included in TCGA, the contribution of ABCB1 mutations to survival rates of major types of cancer may be assessed in the years to come." (PMID 34541464, 2020). "We assessed the impact of ABCB1 mutations on the survival rates in TCGA cancer cases." (PMID 34541464, 2020). "Moreover, in other cancer types, patients with mutations of YB-1 and ABCB-1 genes have decreased overall survival time." (PMID 32041631, 2020). "Moreover, ABCB1 also exhibited a very low mutational frequency in AMLs compared with all types of human cancer." (PMID 34541464, 2020). "Among the three ABC transporters, high ABCB1 expression was associated with increased OS rates consistently across four different cancer types (HNSC, PAAD, SARC, SKCM); high ABCG2 expression was also correlated with increased OS rates in KIRC, consistent with a recent report." (PMID 33202946, 2020). "EVs carrying P-glycoprotein (P-gp, MDR-1 or ABCB1), one of the most well-studied drug efflux pump, have been implicated in the transfer of multidrug resistance to sensitive cells in several human cancer models, such as prostate and ovarian cancers, acute T lymphoblastic leukemia, and osteosarcoma." (PMID 30925923, 2019). "The major ABC transporters responsible for resistance to anti-cancer chemotherapeutics include MDR-1 (P-glycoprotein) encoded by the human ABCB1 gene located on chromosome 7q21 and Breast Cancer Resistance Protein (BCRP) encoded by the human ABCG2 gene located on chromosome 4q22." (PMID 30460040, 2018). "Studies have found that one of the mechanisms of MDR is the overexpression of ATP-binding cassette (ABC) superfamily of transporters in cancer cells, such as P-glycoprotein (P-gp/ABCB1), MDR-associated protein 2 (MRP2/ABCC2), and breast cancer resistance protein (BCRP/ABCG2)." (PMID 29334793, 2018). "Several studies showed that three of the most frequent Single Nucleotide Polymorphisms (SNPs) of ABCB1 (rs1128503, rs2032582, rs1045642) may impact the risk of cancer development, including CRC." (PMID 29282011, 2017). "Previous studies have confirmed that MDR both in cancer cell lines and human tumor tissues is most often associated with the overexpression of the ATP-binding cassette transporter, P-glycoprotein (Pgp), also known as multidrug resistance protein 1 (MRP1), which is encoded by the ABCB1 gene." (PMID 29137448, 2017). "The ABCB1 gene which was also known as MDR1 gene encodes the multi-drug efflux pump P-glycoprotein (P-gp) which is involved in the transport of a wide range of anti-cancer drugs including cisplatin and fluorouracil." (PMID 24340057, 2013). "Previous reports have associated the Wnt/β-catenin pathway with Pgp/ABCB1 regulation in cancer." (PMID 24070327, 2013). "Over the last decades, this hypothesis has led to a proliferation of in vitro reports examining the functionality of ABCB1 gene polymorphisms and the investigation on their potential role in many diseases and cancers." (PMID 22396794, 2012). "Hence the development of diagnostic tests of ABCB1 expression may facilitate attempts for individualized cancer treatments." (PMID 40723843, 2025).
cancer (continued). "Notably, ABCB1, the prototypical ATP-binding cassette transporter initially identified, has been definitively associated with chemoresistance emergence across diverse cancer types." (PMID 40427071, 2025). "It is important to note that a high expression of ABCB1 in tumor cells is associated with poor prognosis and the development of multidrug resistance in a way that makes them attractive prognostic markers with high clinical impact in different types of cancer in adults." (PMID 38674407, 2024). "In addition, the presence of highly frequent polymorphisms in the ABCB1 sequence may contribute to cancer development and significantly determine the disease phenotype." (PMID 36755808, 2023). "Thus, ABCB1 copy number plays an important role in cancer-associated drug resistance." (PMID 36973040, 2023). "Another reason for the low efficiency of cancer treatment is the development of acquired resistance of tumor cells to chemotherapeutic agents, which is frequently caused by the overexpression of specific drug-transporting proteins—ABCB1 (P-glycoprotein), ABCC1 (MRP-1), or ABCG2 (Bcrp)." (PMID 36986696, 2023). "Polymorphisms in the ABCB1 gene have been found to be associated with a susceptibility to ulcerative colitis, Parkinson’s disease, Alzheimer’s disease, cancer, bullous pemphigoid, the osteonecrosis of the femoral head, major depressive disorder and ischemic strokes." (PMID 36432633, 2022). "Moreover, we discovered that sitravatinib could be repositioned into an effective modulator of both ABCB1 and ABCG2 to combat against multidrug resistance associated with the overexpression of ABCB1 or ABCG2 in human cancer cells." (PMID 31941029, 2020). "However, in cancer cells, the overexpression of ABCB1 may cause a decrease in the intracellular accumulation of chemotherapeutic drugs, causing MDR." (PMID 30641875, 2019). "In one study of 60 adult patients with cancer receiving transdermal fentanyl, showed that polymorphisms in the gene ABCB1 could lead to significant changes in fentanyl plasma concentrations, with the ABCB1 1236TT variant being associated with a lower need for rescue medication." (PMID 31547335, 2019). "ABCB1 gene, regulating the exposure to xenobiotics and carcinogens, is associated with the occurrences, development and histopathological features of a broad set of high-grade cancers, including renal epithelial tumors, colorectal cancer and haematological malignancies." (PMID 23050008, 2012). "Although the physiological role of P-gp remains elusive, interindividual expression of the highly polymorphic ABCB1 gene is likely to contribute to variability in the pharmacokinetics and pharmacodynamics of many drugs in addition to increased susceptibility to cancer." (PMID 19626470, 2009). "ABCB1, a polyspecific efflux transporter, mediates multidrug resistance in cancer by interacting with diverse substrates and inhibitors, yet its recognition mechanisms remain elusive." (PMID 41947424, 2026). "ABCB1, also known as P-gp, is a well-established chemoresistance protein that contributes to multidrug resistance in cancer." (PMID 41362671, 2026). "On the other hand, the overexpression of ABCB1 in tumors leads to the progression of MDR in cancer cells against many common drugs that serve as ABCB1 substrates, such as doxorubicin, paclitaxel and vincristine, particularly in CRC." (PMID 41462884, 2025). "To elucidate the molecular mechanisms by which melatonin sensitizes drug‐resistant cells to cancer therapy, we investigated its effects on ABCB1‐overexpressing cells." (PMID 41189280, 2025). "The effect is compromised function of efflux pumps that overcomes the drug resistance of MDR ABCB1‐overexpressing cancer cells both in vitro and in vivo." (PMID 41189280, 2025). "The dual-gold complex QB1561 partially reversed MDR mediated by ABCG2 and effectively suppressed the proliferation of drug-resistant cancer cells overexpressing ABCB1 and ABCG2." (PMID 40066335, 2025).
cancer (continued). "For example, quercetin has been shown to sensitize gastric cancer cells to daunorubicin by downregulating the ABCB1 gene, thereby reducing its overexpression and inhibiting its efflux from cancer cells, while enhancing their apoptosis." (PMID 41154409, 2025). "This is significant because ABCB1 plays a central role in the efflux of DTX from cancer cells, and ABC transporters are critical mechanisms by which chemoresistant cells evade drug accumulation." (PMID 40361461, 2025). "KSQ‐4279, an USP1 inhibitor in clinical trial, widely reversed multidrug resistance in refractory cancers by competing for the drug‐binding pockets of ABCB1/ABCG2/ABCC1 and blocking chemotherapeutic drugs’ efflux." (PMID 41328326, 2025). "Cyclosporin, a well-known immunosuppressive drug, demonstrated high potency to overcome chemoresistance of cancer cells due to its ability to bind with and inhibit the activity of ABCB1." (PMID 41154409, 2025). "The following mechanistic studies unveil that 11a suppresses ABCB1, a major contributor to resistance against numerous anti-cancer drugs, including Romidepsin." (PMID 39809731, 2025). "This amplification correlates with ABCB1 expression in Tx-resistant cells in many different cancer types, notably ovarian cancer." (PMID 41114937, 2025). "ABCB1, ABCC1, and ABCG2 transporter overexpression and COX-2 overexpression are typically linked in cancer." (PMID 40253988, 2025). "MiR-200c downregulation enhances ABCB1 (P-glycoprotein) expression in cancer pharmacogenomics, therefore encouraging drug efflux from tumor cells and hence treatment resistance." (PMID 40430848, 2025). "MDR1 (also known as P-glycoprotein or ABCB1) can contribute to resistance against MCL1 inhibitors by actively exporting these agents from cancer cells, reducing their intracellular levels and therapeutic efficacy." (PMID 41155156, 2025). "Previously, reversal mutation of BRCA2, loss of PARP1 protein expression, and overexpression of drug efflux pumps ABCB1 (p‐glycoprotein) and ABCG2 (BCRP) have been linked to acquired resistance to PAPRi in BRCA2 mutant cancer." (PMID 40874518, 2025). "KSQ‐4279 was shown to significantly elevate the antitumor function of multiple conventional chemotherapeutic drugs in MDR cancer cell lines driven by ABCB1/ABCG2/ABCC1 overexpression in vitro independently on its own cytotoxicity." (PMID 41328326, 2025). "It has been reported that overexpression of ABCB1 is considered a major impediment to the effectiveness of chemotherapy in numerous cancers, which aligns with the findings presented in the present study." (PMID 40175339, 2025). "Researchers have developed gene therapies, which have demonstrated that downregulating ABCB1 expression can also successfully reverse MDR in cancer cells." (PMID 41462884, 2025). "Given the pump‐like function of ABC transporters, the impact of KSQ‐4279 on ABCB1‐, ABCG2‐, and ABCC1‐caused doxorubicin efflux was further evaluated by quantifying the change of doxorubicin inside cancer cells over time." (PMID 41328326, 2025). "By reducing ABCB1 expression, the efflux of anti-cancer drugs from cancer cells is diminished, thereby maintaining higher intracellular drug concentrations." (PMID 39809731, 2025). "Among diverse and complex mechanisms causing MDR, ATP-binding cassette (ABC) transporters—including P-glycoprotein (P-gp, ABCB1), ABCC1, and ABCG2—have been confirmed to be closely associated with MDR and overexpressed in many MDR cancers." (PMID 40509228, 2025). "P-glycoprotein (P-gp, ABCB1)-mediated multidrug resistance (MDR) remains a significant barrier to successful chemotherapy outcomes for cancer patients." (PMID 41235707, 2025). "Studies have demonstrated that CRISPR/Cas9-mediated knockdown of ABCB1 can significantly increase the sensitivity of cancer cells to chemotherapeutic agents, such as doxorubicin." (PMID 40429842, 2025).